C5orf63 (chromosome 5 open reading frame 63)
Synonyms: YDR286C; FLJ44606
Tractability: PROTAC: ubiquitination databases record sites on it.
Gene: Protein-coding gene on chromosome 5 (127,045,235 to 127,073,506, reverse strand). Ensembl gene ENSG00000164241.
Subcellular location (Human Protein Atlas): Mitochondria
Genetic constraint (gnomAD): Loss-of-function variants: 12 observed, 6.87 expected, observed/expected ratio (o/e) 1.75, 90% interval 1.04 to 1.96. That is too few expected variants to judge how well the gene tolerates losing a copy. Missense variants: 55 observed, 64.14 expected, observed/expected ratio (o/e) 0.86, 90% interval 0.69 to 1.07. Synonymous variants: 17 observed, 21.5 expected, observed/expected ratio (o/e) 0.79, 90% interval 0.54 to 1.19.
Homologues: Orthologues: macaque C6H5orf63 (97% identical), guinea pig C5orf63 (85% identical), pig C5orf63 (85% identical), dog C5orf63 (84% identical), mouse C330018D20Rik (83% identical), rat C18h5orf63 (82% identical), rabbit C5orf63 (79% identical), zebrafish C10H5orf63 (52% identical), tropical clawed frog C5orf63 (45% identical).
Diseases named in the same sentence as C5orf63 in open-access papers:
C5orf63 is named in the same sentence as 1 disease in open-access papers, as found by Europe PMC text mining. Sharing a sentence is not in itself a finding about the gene and the disease.
C5orf63 shares sentences with these, for which no sentence is quoted: tumour (1 paper).